HNF4A (hepatocyte nuclear factor 4 alpha)
Diseases named in the same sentence as HNF4A in open-access papers (continued):
Sharing a sentence is not in itself a finding about the gene and the disease.
colon carcinoma (continued). "In summary, HNF4α isoforms perform non-redundant functions in the colon under conditions of stress, underscoring the importance of tracking them both in colitis and colon cancer." (PMID 27166517, 2016). "Besides, overexpression of HNF4α inhibited EMT via modulating Wnt/β-catenin signaling and suppressing the expression of Snail, Slug, Twist, and Vimentin while inducing E-cadherin expression in colon cancer cells." (PMID 38372868, 2024). "Although some studies did not distinguish between the different HNF4α genes and protein isoforms, several recent studies showed that ectopic expression of P1-HNF4α but not P2-HNF4α reduced the tumorigenic potential of HCT116 human colon cancer cells in a mouse xenograft model." (PMID 33462379, 2021). "Overall, these data indicate that HOTAIR is directly repressed by HNF4α, both in the stable maintenance of epithelial identity and during MET transdifferentiation, whereas HOTAIR gene repression is released by HNF4α impairment, both in hepatocytes and in colon carcinoma cells." (PMID 30154449, 2019). "We recently showed that ectopic expression of P1- but not P2-HNF4α decreased the tumorigenic potential of the human colon cancer cell line HCT116 in a mouse xenograft model, suggesting that the different HNF4α isoforms may indeed play distinct roles in the colon." (PMID 27166517, 2016). "Indeed, HNF4G expression, not HNF4A, correlated with BTNL3/BTNL8 expression and γδ T-cell infiltration into tumors in our human colon cancer dataset." (PMID 37309673, 2023).
liver fibrosis (44 papers, 2014 to 2025). "It is reported that HNF4A can alleviate acute liver injury generated by acetaminophen and liver fibrosis caused by toxins and cholestasis." (PMID 39979267, 2025). "Taken together, these results imply TRPM8 deficiency may attenuate liver fibrosis by downregulating the expression of the pro-inflammatory factor S100A9 while promoting the expression of HNF4α." (PMID 35525986, 2022). "Given that an mRNA-based strategy has been developed to target HNF4A in preclinical models for liver fibrosis, similar strategy can be used to control the development of gastrointestinal adenocarcinoma with HNF4A-dependent overexpression of MYB." (PMID 40234694, 2025). "In contrast, the activity of HNF4α and HNF1α, which are central regulators of hepatic differentiation and known to inhibit epithelial‐to‐mesenchymal transition in liver fibrosis, were significantly reduced." (PMID 39605182, 2025). "The human hepatocyte nuclear factor 4 alpha (HNF4A) delivered via lipid nanoparticle messenger RNA (LNP-mRNA) can significantly mitigate the degree of liver fibrosis and restore hepatic cellular activity in mouse models." (PMID 39460333, 2024). "The expression of HNF4A leads to the restoration of metabolic function and reversing (attenuation) of liver fibrosis and cirrhosis via controlling macrophages and hepatic stellate cells." (PMID 38157373, 2023). "For example, re-expression of HNF4A was shown to inhibit fibrosis in four independent mouse models of liver fibrosis." (PMID 38144457, 2023). "HNF4A, which controls liver function, is known to be inhibited by increased inflammation (immune activity) in liver fibrosis." (PMID 38157373, 2023). "Paraoxonasel is a direct target of HNF4α and participates in the weakening of liver fibrosis mediated by HNF4α." (PMID 36249028, 2022). "HNF4α inhibition increased hepatic fat accumulation, but it attenuated steatohepatitis, as well as hepatic fibrosis, via reduction of bile acid toxicity." (PMID 36362837, 2022). "Taken together, these data clearly demonstrate a critical gene-dosage-dependent role of HNF4α in maintaining hepatocyte differentiation and suppressing hepatocyte proliferation, cholangiocyte transdifferentiation, and liver fibrosis during HFHS intake." (PMID 35614477, 2022). "HNF-4α is a master regulator of hepatocyte phenotype and a key factor in xenobiotic metabolism, and reduced expression of HNF-4α has been reported in liver fibrosis." (PMID 36361872, 2022). "It was reported that stress-induced inhibition of HNF4A expression is related to liver fibrosis and cancer formation." (PMID 32570707, 2020). "Most significantly, HNF4α and HNF1α delivery in animal models attenuates liver fibrosis and inhibits growth of xenograft tumors." (PMID 31543815, 2019). "Hnf4a is a central transcriptional regulator of hepatocyte differentiation, and is also known to attenuate hepatic fibrosis induced by portal impairment in our PCS group." (PMID 26020934, 2015). "As a result of ancestral BPA exposure, the downregulation of hnf4a and overexpression of xbp1 and atf4 could have induced liver fibrosis and progressed the NAFLD to NASH phenotype in medaka." (PMID 38826193, 2024). "Moreover, resetting the hepatocyte-specific transcriptional network, particularly HNF4α, preserves hepatocyte function and inhibits liver fibrosis." (PMID 39684823, 2024). "Further, HNF4α is a central transcriptional regulator of hepatocyte gene expression, differentiation, and function maintenance and has been proven to play a central regulatory role in alleviating liver fibrosis." (PMID 37569884, 2023). "Mechanistically, FN1 expressed from iECs led to the upregulation of Itgα5/β1 and Hnf4α in iHEAs and were correlated to the decreased expression of genes related to hepatic stellate cell activation such as Lox and Spp1 in the cholestatic liver fibrosis animals." (PMID 35883684, 2022).
liver fibrosis (continued). "EGFP-MSCs could reduce the hepatocyte necrosis and liver fibrosis induced by CCl4, and HNF-4α enhanced the effect of MSCs." (PMID 31133062, 2019). "Furthermore, this is highly expressed in the liver, kidneys and intestines, but is downregulated in the pancreas, stomach and epididymis in adult vertebrates.In the study of hepatic fibrosis, it was found that the progression of hepatic fibrosis was correlated to the decreased expression of Hnf4α." (PMID 33777519, 2021). "Inhibition of hepatocarcinogenesis by enforced expression of HNF4α has been extensively studied, and it attenuates hepatocyte EMT and alleviates liver fibrosis." (PMID 38993564, 2024). "For instance, in the liver, increased extracellular matrix rigidity secondary to liver fibrosis activates YAP nuclear translocation and results in HNF4α downregulation." (PMID 37974020, 2023). "The inhibition of TRPM8 has the potential to mitigate liver fibrosis by downregulating the expression of the pro-inflammatory factor S100A9 and promoting the expression of HNF4α." (PMID 37569884, 2023). "In accordance with these findings, our data show that inhibition of TRPM8 upregulated the expression of HNF4α in both CCl4- and BDL-treated models, suggesting its involvement in the process of liver fibrosis." (PMID 35525986, 2022). "Because 78% of TdTom-positive cells in the BDL livers expressed HNF4α, we concluded that hepatocytes are the major cell type in which Prom1 is upregulated during BDL-induced liver fibrosis." (PMID 36038590, 2022). "MiR-21 modulates ERK1 signaling and EMT in liver fibrosis by regulating SPRY2 and HNF4α expression." (PMID 25303175, 2014). "Furthermore, the miR‐371‐373 cluster within EXOs from intestinal cells might alleviate liver fibrosis by promoting the hepatic differentiation of HPCs via RPS6KA2 and its interaction with CREB2 and HNF4A." (PMID 40619613, 2025). "Additionally, HNF4α, the liver-enriched transcription factor, could attenuate hepatic fibrosis by improving liver function and alleviating EMT in hepatic fibrosis." (PMID 25303175, 2014). "As a proof-of-concept study, HNF4α gene was efficiently posttranscriptional activated by the CRISPR/dCas9-VP64 mediated activation system in HSCs, while HNF4α is a transcriptional regulatory factor of hepatocytes differentiation and HNF4α could significantly attenuate hepatic fibrosis." (PMID 33336604, 2021).
Obesity (41 papers, 2007 to 2025). Accumulation of substantial excess body fat. "In conclusion, only five of the 37 genetic variants previously linked to T2DM and obesity in the Saudi Arabian population [HNF4A-rs4812829, WFS1-rs1801214, DUSP9-rs5945326, ZFAND6-rs11634397, FTO-rs11642841] were associated with prediabetes susceptibility." (PMID 36980809, 2023). "A site of significant HNF4α expression is the kidney, and obesity is a strong risk factor for the development of renal disease." (PMID 34117215, 2021). "In line with this, several HNF4α genetic variants have been associated with obesity-related metabolic disorders in children and adolescents." (PMID 30925463, 2019). "Most studies have reported the associations between POMC, MC4R, and HNF4A variants and obesity and MetS-related phenotypes." (PMID 29598821, 2018). "However, whether the HNF4α alleles link low SHBG levels to obesity and metabolic disorders remains unclear." (PMID 30925463, 2019). "Several relevant transcription factors (TFs) bind to the promoter region of ZPR1, including PPARG (functioning in insulin sensitivity and obesity) and HNF4A (triggering genes involved in glucose, fatty acid, and cholesterol metabolism)." (PMID 40665476, 2025). "Here, we administered NCT to mice fed a high fat diet, with the goal of studying the role of HNF4α in obesity-related diseases." (PMID 35385524, 2022). "Patients with non-alcoholic steatohepatitis (NASH) have also been characterized by low hepatic HNF4A expression, in line with the dramatically decreased HNF4A levels observed in livers from mice with genetic or diet-induced obesity." (PMID 32998360, 2020). "Next, we performed ChIP-seq to understand how Hnf4α localization responds to obesity (2 animals per group)." (PMID 32075973, 2020). "In our study, genes downregulated in obesity were enriched in HNF4α binding sites and HNF4α levels were slightly higher in obese animals at these sites." (PMID 29361968, 2018). "Taken together, these findings indicate that HNF4α may play a role in diet-induced obesity and metabolic syndrome, and that the isoforms may play distinct roles." (PMID 41167395, 2025). "Similarly, other SNP variants of HNF4A and HNFG can cause increased susceptibility to ulcerative colitis, Crohn’s disease and obesity." (PMID 37635981, 2023). "Very interestingly, obesity and elevated blood triglycerides are associated with a high frequency of T130I mutation of HNF4α in non-diabetic indigenous Mexicans with high intake of HFHS." (PMID 35614477, 2022). "Focusing on obesity was logical, as we had shown previously that fatty acids are HNF4α antagonists." (PMID 35385524, 2022). "Likewise, in the intestine, HNF4A also serves as a modulator of the epigenome and transcriptome in diet-induced obesity." (PMID 32998360, 2020). "To understand whether diet and obesity can affect the distribution of a model signal responsive transcription factor, we carried out ChIP-seq for the nuclear receptor HNF4α in lean and obese male mice." (PMID 29361968, 2018). "We found obesity can affect HNF4α bindng and reprogram gene expression in colon epithelium." (PMID 29361968, 2018). "We next considered whether the HVRs were enriched for either the occupancy of three specific transcription factors (HNF4A, CEBPA, and FOXA1) or the 418 rat orthologues of Human GWAS variants associated with obesity and metabolic traits." (PMID 29272997, 2017). "SULT2B1 was previously known to decrease serum and hepatic lipid levels by deactivating the oxysteroid-derivative endogenous LXR agonists, and inhibit gluconeogenesis by targeting HNF4α, both of which may have contributed to the alleviation of metabolic abnormalities in obesity." (PMID 40456448, 2025). "While glycemic control and the progression of complications can be effectively managed in HNF4A-MODY patients receiving long-term insulin therapy, the potential risks of hypoglycemic episodes, obesity, and atherosclerosis remain significant concerns." (PMID 40589512, 2025).
Obesity (continued). "For instance, within an HNF-4α/MODY1 pedigree, obesity was observed in two diabetic members, one being a 7-year-old with fasting plasma glucose of 203 mg/dL and fasting insulin of 27 μU/mL." (PMID 38333726, 2023). "The principal finding reported here is that in a mouse model of diet-induced obesity the genes induced by NCT, a potent HNF4α agonist, were highly relevant to IBD." (PMID 35385524, 2022). "Accordingly, S1PR3, IQCG, and TF are common in HCL, aging, and CVD; ACSL1, THBD, and HNF4A are repeated in HTN, obesity, and CVD." (PMID 36035865, 2022). "Several of the observed DMCs were located in genes related to T2D or obesity, such as ALOX12, PAMR1, and GNAS in WB; IRS1, LEP, and ADIPOQ in SAT; LCAT, FOXA2, KCNQ1, and GCKR in VAT; and PKD4, HNF4A, XBP1, and PON1 in LT." (PMID 29466957, 2018). "Glycemic control and complication progression could be acceptable in HNF4A-MODY cases treated with long-time insulin, but risks of hypoglycemic events, obesity, and atherosclerosis remain." (PMID 40589512, 2025). "To investigate if the inability of the β cell lacking HNF4α in response to obesity was due to a structural adaptation failure we analyzed the islet architecture and observed that the HFD-induced increase in β-cell mass expansion was not noticed in KO/HFD mice." (PMID 39741884, 2024). "Here the authors show that HNF4A is not required for intestinal lipid metabolism but controls energy expenditure under diet induced obesity through the fat-induced release of glucose-dependent insulinotropic polypeptide." (PMID 35017517, 2022). "Determining whether such a regulatory circuit between HNF4A and GIP is of functional importance in normal and diseased individuals with obesity requires further investigation." (PMID 35017517, 2022). "There is a complex relationship between obesity, fatty acids, and IBD, and the data presented here suggest that HNF4α may be important in their interrelationship." (PMID 35385524, 2022). "Here we show that intestinal HNF4A is not required for intestinal lipid metabolism per se, but unexpectedly influences whole-body energy expenditure in diet-induced obesity (DIO)." (PMID 35017517, 2022). "Five variants were top weighted (above the threshold of 0.75) in more than one cluster: CDC123/CAMKID (Beta Cell and Proinsulin), HSD17B12 (Beta Cell and Obesity), ADCY5 (Beta Cell and Lipodystrophy), CCND2 (Proinsulin and Lipodystrophy), and HNF4A (Beta Cell and Proinsulin)." (PMID 30240442, 2018). "Interestingly, because megalin is invovled in obesity/metabolic syndrome-related CKD, we investigated whether HNF4α directly transactivates the expression of megalin." (PMID 30582012, 2019). "Interestingly, the HNF4α exon swap mice, which are resistant to the SO-induced obesity, had high levels of LA in the liver indicating that LA itself does not correlate with obesity and supporting the notion that it is the ratio of LA/ALA to LA/ALA diols that drives SO-induced obesity." (PMID 41167395, 2025).
Hepatic steatosis (39 papers, 2011 to 2025). Steatosis is a term used to denote lipid accumulation within hepatocytes. "Liver-specific HNF4α −/− mice showed severe fatty liver in association with disruption of very low density lipoprotein (VLDL) secretion." (PMID 36362837, 2022). "PPARA is a transcription factor that has been implicated in hepatic steatosis and hepatic metabolic homeostasis through regulation of the hepatocyte nuclear factor-4 alpha (HNF4A) gene." (PMID 26206264, 2015). "Loss of HNF4α contributes to lipid accumulation, steatosis, and progression to fatty liver disease." (PMID 40158182, 2025). "Targeting HNF4α could affect multiple nuclear receptors beyond the HNF4α-PPARα axis, potentially improving sepsis-associated hepatic steatosis, cholestasis, apoptosis, and alterations in drug metabolism." (PMID 39261648, 2024). "Other similar studies have shown that hepatic HNF4α deletion causes fatty liver in mice." (PMID 36362837, 2022). "Circulating miRNAs (e.g., miR-122, miR-34a) and epigenetic markers (e.g., HNF4A methylation) show promise for reflecting BPA-induced hepatic steatosis and ERα-mediated lipid dysregulation." (PMID 40475995, 2025). "NCT was introduced as a potential NAFLD drug candidate due to its ability to recover HNF4α expression and reduce hepatic steatosis." (PMID 39261648, 2024). "In this regard, the HNF4α agonist NCT is protective in experimental models of high-fat diet by reducing hepatic steatosis." (PMID 39261648, 2024). "Silencing the HNF4A gene in mice improved glucose tolerance and insulin sensitivity, with beneficial outcomes for liver steatosis and fibrosis." (PMID 39459592, 2024). "Due to the increased lethality of sepsis in Hnf4aLiver-i-KO mice, we expected HNF4α depletion to worsen hepatic steatosis." (PMID 39261648, 2024). "SIRT2 has been shown to prevent hepatic steatosis and metabolic disorders through the deacetylation of HNF4α, and the upregulation of HNF4α acetylation levels increases hepatic lipid accumulation." (PMID 37239836, 2023). "What is more, it has been reported that 6-gingerol ameliorates hepatic steatosis via the HNF4α/miR-467b-3p/GPT1 pathway, which provides another research strategy." (PMID 37047258, 2023). "Previously, we showed that intraperitoneal (IP) administration of NCT reversed hepatic steatosis in obese mice fed a high fat diet (HFD) through a previously unsuspected pathway involving regulation by HNF4α of dihydroceramide synthesis." (PMID 35087037, 2022). "In summary, we uncover the protective role of hepatic PRMT1 against liver steatosis in obese subjects by induction of hepatic fatty acid oxidation via HNF-4α and PGC-1α dependent mechanism." (PMID 35401831, 2022). "Hepatocyte nuclear factor 4α (HNF4α) and glucocorticoid receptor (GR), master regulators of liver metabolism, are down-regulated in fatty liver diseases." (PMID 35614477, 2022). "Stimulation of HNF4α activity with the HNF4α agonist NCT led to reversal of hepatic steatosis in the short time frame of two weeks." (PMID 34117215, 2021). "Ingestion of a high level of dietary fat will lead to constitutive downregulation of HNF4α activity and thus to hepatic steatosis." (PMID 34117215, 2021). "For example, knock-down of HNF4a induces fatty liver disease in normal mice by inhibiting secretion of VLDLs33." (PMID 31332246, 2019). "In human liver tissues, SHBG and HNF4α mRNA expression decreased along with the elevated grade of hepatic steatosis." (PMID 30455723, 2018). "Additionally, long-term oral administration of the HNF4α agonist N-trans-caffeoyltyramine (NCT) prevents hepatic steatosis." (PMID 40920830, 2025). "In the context of hepatic metabolism, Sirt2 emerges as a protector against fatty liver disease and hepatic steatosis by stabilizing HNF4α via deacetylation, thus promoting the expression of genes involved in lipid, amino acid, and glucose metabolism, and influencing inflammatory networks." (PMID 39334926, 2024).